PCNAP1 (proliferating cell nuclear antigen pseudogene 1)
Synonyms: p1PCNA
Gene: Transcribed processed pseudogene on chromosome 4 (99,160,937 to 99,161,645, reverse strand). Ensembl gene ENSG00000249065.
Diseases named in the same sentence as PCNAP1 in open-access papers:
PCNAP1 is named in the same sentence as 10 diseases in open-access papers, as found by Europe PMC text mining. Sharing a sentence is not in itself a finding about the gene and the disease. The quoted sentences say what the papers report.
hepatoma (5 papers, 2019 to 2025). "Further comparative analyses involving healthy controls, gastric cancer (GC), and CRC groups revealed significantly higher PCNAP1 levels in hepatocellular carcinoma patient plasma." (PMID 40556338, 2025). "The aim of this study was to evaluate the expression level and clinical significance of the lncRNA, proliferating cell nuclear antigen pseudogene 1 (PCNAP1), in cancer tissue and the plasma of patients with hepatocellular carcinoma (HCC)." (PMID 35224110, 2022). "A previous study has indicated that PCNAP1 promotes the proliferation of hepatoma cell lines, HepG2 and HepG2.2.15." (PMID 34007276, 2021). "Our data showed that PCNAP1/PCNA signaling significantly promoted the growth of hepatoma cells in vitro and in vivo." (PMID 31410212, 2019). "Although the functional analyses of PCNAP1 were performed using hepatoma cell lines and clinical HCC tissues, the upregulation of PCNAP1 might also be observed in HBV-infected humanized mice." (PMID 34696350, 2021). "To investigate whether PCNAP1 also influences the proliferation of other hepatoma cell lines, we selected two hepatoma cell lines, Huh7 and SNU-182." (PMID 34007276, 2021). "As expected, we found that PCNAP1 sponged miR-154 to stimulate PCNA expression in hepatoma cells." (PMID 31410212, 2019). "Given that the pseudogenes played multiple roles through modulating their ancestral genes 12, we concerned whether the pseudogene PCNAP1 modulated its ancestor PCNA in hepatoma cells." (PMID 31410212, 2019). "Accordingly, we concerned whether PCNAP1 could promote the proliferation of hepatoma cells through modulating the expression of miR-154 and PCNA." (PMID 31410212, 2019). "Interestingly, a 10-20 fold higher expression of PCNAP1 was observed in HBV+ hepatoma cells relative to HBV- ones." (PMID 31410212, 2019). "It suggests that the pseudogene PCNAP1 is able to modulate HBV replication in hepatoma cells." (PMID 31410212, 2019). "Thus, we conclude that PCNAP1 and PCNA significantly promotes the growth of hepatoma cells in vitro and in vivo." (PMID 31410212, 2019). "Thereby, we concerned whether PCNAP1/PCNA signaling, as a regulating factor of HBV replication and cccDNA accumulation, could promote the proliferation of hepatoma cells." (PMID 31410212, 2019).
gastric cancer (2 papers, 2022 to 2025). A primary or metastatic malignant neoplasm involving the stomach. "Plasma PCNAP1 may have a clinical diagnostic value for HCC patients; in that compared to other gastrointestinal tumors (gastric cancer and colorectal), the level of PCNAP1 was found to be greater (P < 0.05)." (PMID 35224110, 2022). "The plasma levels of PCNAP1 in patients with HCC, HC, gastric cancer, and colorectal cancer were 2.15 ± 1.20, 0.82 ± 0.67, 1.00 ± 0.73, and 0.89 ± 0.63, respectively." (PMID 35224110, 2022). "Compared to the healthy control group, a gastric cancer group, and a colorectal cancer group, HCC patient plasma levels of PCNAP1 were significantly greater (P < 0.01)." (PMID 35224110, 2022). "Compared to the HC group, the level of PCNAP1 in gastric cancer and colorectal cancer groups was not significantly increased and was not statistically significant (the t values were 1.90 and 0.74, respectively; the P values were 0.06 and 0.46, respectively)." (PMID 35224110, 2022).
liver cancer (2 papers, 2019 to 2022). An epithelial or non-epithelial malignant neoplasm that arises from the liver. "Clinically, the expression levels of PCNAP1 were remarkably elevated in the HBV cccDNA-positive liver cancer tissues." (PMID 31410212, 2019). "Further, PCNAP1 levels in liver cancer tissue were significantly greater than in adjacent tissue (P < 0.01), suggesting that PCNAP1 may be a new biomarker for HCC diagnosis." (PMID 35224110, 2022). "Therefore, we conclude that the pseudogene PCNAP1 promotes HBV replication and cccDNA accumulation in liver cancer." (PMID 31410212, 2019). "Additionally, the knockdown of PCNAP1 dose-dependently decreased the expression levels of PCNA in HepG2.2.15 and PLC/PRF/5 cells, indicating that PCNAP1 is able to up-regulate PCNA in liver cancer." (PMID 31410212, 2019).
colorectal cancer (1 paper, 2022). A primary or metastatic malignant neoplasm that affects the colon or rectum. "Interestingly, the AUC for chronic gastric cancer and colorectal cancer were 0.57 and 0.54, indicating that PCNAP1 was significantly more advantageous for the diagnosis of HCC." (PMID 35224110, 2022).
lymph node metastasis (1 paper, 2022). "The PCNAP1 levels were related to the TNM stage, lymph node metastasis, and tumor maximum diameter (P < 0.05) but were not related to gender and age (P = 0.459 and 0.656)." (PMID 35224110, 2022).
tumor (5 papers, 2019 to 2024). "PCNAP1 acts as a ceRNA to sponge the tumor suppressor miR-154, preventing it from repressing PCNA expression." (PMID 36203765, 2022). "It suggests that PCNAP1 up-regulates the expression of PCNA by competing for the tumor-suppressive miR-154." (PMID 31410212, 2019). "IHC staining further confirmed that the expression of Ki-67, a marker of proliferation, was markedly decreased in the tumor tissues from the nude mice transplanted with HepG2.2.15 and HepG2 cells treated with PCNAP1 siRNA or PCNA siRNA." (PMID 31410212, 2019). "It suggests that miR-154 as a potential tumor suppressor is involved in modulation of PCNAP1/PCNA signaling." (PMID 31410212, 2019). "The expression levels of PCNAP1 in tumor and adjacent tissue were assessed by qRT-PCR assay." (PMID 35224110, 2022). "Further, PCNAP1 in cancer tissue of HCC patients was related to TNM staging, lymph node metastasis, and maximum tumor diameter." (PMID 35224110, 2022). "We found the expression of PCNAP1 to be at relatively high and stable levels in cancer tissue and the plasma of HCC patients, and that PCNAP1 levels correlated with alpha-fetoprotein (AFP), a clinical tumor marker of HCC." (PMID 35224110, 2022). "LncRNA PCNAP1 is a pseudogene of PCNA highly expressed in HBV-positive HCC cells and tumor tissue." (PMID 36203765, 2022). "PCNAP1 is highly expressed in HBV-positive HCC cells and patient tumor tissues." (PMID 35154157, 2022). "Further, HCC expression of PCNAP1 was related to TNM clinical stage, lymph node metastasis, and maximum tumor diameter (χ2 = 10.337, 6.718, and 8.164; P < 0.05), but not related to gender or age (χ2 = 6.228 and 5.309; P = 0.459 and 0.656)." (PMID 35224110, 2022).
cancer (3 papers, 2018 to 2022). A tumor composed of atypical neoplastic, often pleomorphic cells that invade other tissues. "Spearman's rank correlation analysis showed that the level of PCNAP1 in plasma of HCC patients was positively related to the expression of PCNAP1 in cancer tissue (r = 0.54, P < 0.01)." (PMID 35224110, 2022). "This study analyzed the expression of PCNAP1 in the cancer tissue and plasma of HCC patients and found relationships among PCNAP1 and patient clinicopathological characteristics." (PMID 35224110, 2022). "Spearman's rank correlation analysis was performed to assess relationships among cancer tissue, plasma PCNAP1, and plasma AFP." (PMID 35224110, 2022). "This study demonstrated PCNAP1 in the cancer tissue and plasma of HCC patients." (PMID 35224110, 2022). "Further, cancer tissue PCNAP1 was shown to relate to clinical symptoms of HCC patients." (PMID 35224110, 2022). "Hence, new research should be focused on this pseudogene and cancer to explain why PCNAP1 appeared in a relevant 19th position in the gene signature." (PMID 30458775, 2018). "There was a positive relationship between PCNAP1 and AFP in the plasma of HCC patients (r = 0.41, P < 0.01), and the level of PCNAP1 in plasma was also positively related to PCNAP1 in cancer tissue (r = 0.54, P < 0.01)." (PMID 35224110, 2022). "Further, it is necessary to confirm the role of PCNAP1 in HCC, as well as in cancer cell differentiation, infiltration, metastasis, clinical treatment, and prognosis." (PMID 35224110, 2022). "The functional analysis performed to the genetic signature obtained with the Gene-disease approach showed a significant presence of genes related with cancer, as well as one gene (IFNK) and one pseudogene (PCNAP1) which a priori had not been described to be related with cancer." (PMID 30458775, 2018).
gastrointestinal tumors (1 paper, 2022). "Moreover, levels of PCNAP1 were found to distinguish HCC from other gastrointestinal tumors." (PMID 35224110, 2022).
PCNAP1 also shares sentences with these, for which no sentence is quoted: breast carcinoma (1 paper); viral infection (1).